HK2 (hexokinase 2)
Diseases named in the same sentence as HK2 in open-access papers (continued):
Sharing a sentence is not in itself a finding about the gene and the disease.
Stroke (6 papers, 2023 to 2025). Sudden impairment of blood flow to a part of the brain due to occlusion or rupture of an artery to the brain. "It has been shown that stroke-induced up-regulation of monocyte hexokinase 2 (Hk2) depends on HMGB1, thus mediating vascular inflammation and atherosclerosis progression after stroke." (PMID 38740617, 2025). "The effects of HK2 inhibitors on functional recovery were evaluated in mice treated with 3BP (or vehicle) initiated 3 h after stroke, with dosing repeated twice daily for the subsequent 3 days." (PMID 41152941, 2025). "It remains uncertain why immune cells require HK2-dependent glycolysis when activated, but this property nevertheless identifies HK2 as a target for suppressing post-stroke inflammation." (PMID 41152941, 2025). "Histological assessments performed in parallel were used to correlate microglial gene expression with microglial morphology changes after stroke and to determine HK2 inhibitor effects on secondary neuronal injury in the peri-infarct cortex." (PMID 41152941, 2025). "Glycolytic metabolic processes, particularly enzymes like HK2, PFKFB3, PKM2, PDH, LHD, and metabolites such as lactate, have emerged as potential predictors of stroke risk, development, and prognosis." (PMID 39926015, 2025). "Mice treated with the HK2 inhibitor 3-bromopyruvate for four days after stroke showed long-term improvement in functional outcomes." (PMID 41152941, 2025). "Selective HK2 inhibitors provide a clinically applicable approach for suppressing microglial activation and thereby improving outcomes after stroke." (PMID 41152941, 2025). "The present study aimed to evaluate effects of HK2 inhibition when initiated at a time point with clinical applicability, several hours after stroke." (PMID 41152941, 2025). "Accordingly, HK2 inhibitors may selectively target immune cells to suppress post-stroke inflammation." (PMID 41152941, 2025). "Interestingly, a recent study found that HK2 knockdown exacerbated neuroinflammation and worsened brain injury in a photothrombotic stroke model." (PMID 39926015, 2025). "In the peri-infarct-1 region, HK2 inhibitors attenuated the upregulation of pro-inflammatory gene expression observed in microglia at 12 h after stroke, and this correlated with a suppression of CD11b upregulation and the classical morphological changes observed at 48 h after stroke." (PMID 41152941, 2025). "Here we compared the effects of the non-selective hexokinase inhibitor 2-deoxyglucose to the HK2-selective inhibitors lonidamine and 3-bromopyruvate on gene expression changes and secondary injury after stroke." (PMID 41152941, 2025). "In conclusion, this study reveals a non-metabolic role of HK2 in exosomes biogenesis via its protein kinase activity, offering a potential therapeutic target for stroke." (PMID 40720706, 2025). "Salutary effects of selective HK2 inhibition have been reported in stroke, though not using the clinically relevant, delayed administration or with the long-term behavioral endpoints assessments used here." (PMID 41152941, 2025).
tongue squamous cell carcinoma (6 papers, 2017 to 2022). A squamous cell carcinoma that arises from the tongue. "HK2/PKM2 knock-down significantly inhibited the growth of tongue squamous cell carcinoma, transplanted tumors, and lung metastasis in mice." (PMID 35845594, 2022). "A hypoxic environment increases HK2 expression and the migration and invasion ability of tongue squamous cell carcinoma cells." (PMID 31027222, 2019). "In addition, overexpression of HK2 enhances the metastatic potential of tongue squamous cell carcinoma via the SOD2-H2O2 pathway." (PMID 32424132, 2020). "Increased expression of HK2 has been shown to promote EMT both in vitro and in vivo through an enhanced glycolytic phenotype under hypoxic conditions in tongue squamous cell carcinoma." (PMID 31027222, 2019).
cardiac ischemia (5 papers, 2016 to 2024). "We previously demonstrated that hexokinase II (HK2) dissociation from mitochondria during cardiac ischemia correlates with cytochrome c (cyt-c) loss, oxidative stress and subsequent reperfusion injury." (PMID 32579577, 2020).
gastric adenocarcinoma (5 papers, 2019 to 2022). "Results showed that this cotreatment modulated numerous critical proteins, such as EGFR/HER2/HER3, Kras/ERK/Vimentin, and mTOR/HIF1-α/HK2/LDHA pathways of gastric adenocarcinoma AGS cells." (PMID 36145507, 2022). "Normal mucosa (NM) and primary tumor (PT) of 40 metastatic gastric adenocarcinomas patients who received second-line paclitaxel-ramucirumab (PR) were analyzed for mRNA expression of the following genes: HK-1, HK-2, PKM-2, LDH-A, and GLUT-1." (PMID 32372141, 2020).
renal carcinoma (5 papers, 2016 to 2022). A carcinoma arising from the epithelium of the renal parenchyma or the renal pelvis. "High expression of HK2 was also associated with the poor survival and prognosis of renal cancer patients." (PMID 35265223, 2022). "However, current findings show a significant association of HK2 with immune cell infiltration, survival, and prognosis of renal cancer patients." (PMID 35265223, 2022). "Next, we also determined the mRNA and protein expression levels of HK2 in renal cancer and normal cell lines." (PMID 35265223, 2022). "In this study, RNA-seq data from renal cancer and normal tissues were extracted from TCGA and the relationship between HK2 expression and pathological features of RCC patients was analyzed using the GEPIA and UALCAN databases." (PMID 35265223, 2022). "The HK2 expression in renal carcinoma cell lines was also significantly higher than that in normal renal cell lines." (PMID 35265223, 2022). "Interestingly, a different group recently reported that miR-145 targets hexokinase 2, which regulates the first step of glycolysis, in renal cancer cells." (PMID 28380435, 2017). "In conclusion, upregulated HK2 expression promotes glycolysis and participates in the tumorigenesis and progression of RCC, playing an increasingly vital role in renal cancer." (PMID 35265223, 2022). "Therefore, we explored the relationships between PD-L1 levels and glucose metabolism related enzymes (GLUT1, HK2, and LDHA) in renal cancer, which showed that only LDHA levels correlated positively with PD-L1 levels." (PMID 36267974, 2022).
renal fibrosis (5 papers, 2022 to 2026). A final common manifestation of a wide variety of chronic kidney diseases characterized by glomerulosclerosis and tubulointerstitial fibrosis. "In addition to regulating lipid metabolism to alleviate renal fibrosis, it also inhibits glycolysis by reducing the expression of HK2 and lactate dehydrogenase A (LDHA) in NRK-52E cells." (PMID 39465434, 2024). "Hexokinase 1 (HK1) and Hexokinase 2 (HK2) are HK isoenzymes that participate in the proximal step of glycolysis, and these have been recently reported to have a significant role in glycolysis, during the development of renal fibrosis." (PMID 34983531, 2022). "Subsequently, immunohistochemistry staining was performed to identify the site where glycolysis occurs in the kidney, which revealed that HK2 was predominantly expressed in TECs, suggesting that a metabolic switch to glycolysis occurs in TECs during renal fibrosis." (PMID 36253358, 2022). "In our study, we found that PC knockout in mice increased mtDNA leakage, significantly activated the cGAS‐STING pathway, and subsequently upregulated the expression of glycolytic enzymes such as HK2 and PKM2, promoting renal fibrosis." (PMID 39836535, 2025). "Additionally, qRT‐PCR analysis revealed a significant increase in the expression of HK2 and PFKP, key genes involved in the hypoxia response, underscoring the metabolic reprogramming that contributes to renal fibrosis under heat stress." (PMID 41573374, 2026). "Moreover, during renal fibrosis, several signaling pathways and glycolysis-related enzymes, such as the TGF-β, HIF-1α, and PI3K/Akt pathways, hexokinase 2 (HK2), phosphofructokinase-1 (PFK1), and PKM2, are activated." (PMID 39465434, 2024).
type 1 diabetes mellitus (5 papers, 2011 to 2023). A chronic condition characterized by minimal or absent production of insulin by the pancreas. "Reduced expression of HK2 is also associated with non-insulin-dependent diabetes, which may lead to osteoporosis and losses in lean mass." (PMID 22087292, 2011). "We investigated miRNAs hypothetically involved in GLUT4/HK2 expression in soleus muscle of type 1 diabetes-like rats." (PMID 30258406, 2018). "For the same reason, the expression of HK2 is decreased in type 1 diabetes mellitus (T1DM) due to reduced insulin signaling and is recovered upon insulin treatment in T1DM." (PMID 37109475, 2023).
brain cancer (4 papers, 2016 to 2025). A primary or metastatic malignant neoplasm affecting the brain. "Hexokinase 2 (HK2), a well-known hypoxia-inducible gene, has been described to be upregulated in different types of brain cancers and correlated with EMT." (PMID 32793478, 2020). "For instance, VEGFA, HK2, and LDHA are linked to the HIF-1 signaling pathway and glycolysis/gluconeogenesis, underscoring their roles in the metabolic adaptations of the metastatic brain cancer cells." (PMID 40038276, 2025).
diabetic retinopathy (4 papers, 2021 to 2025). "Evidence of all of these effector pathways and biomarkers of HK2-linked glycolytic overload and unscheduled glycolysis has been found in diabetic endothelial dysfunction, DKD, diabetic retinopathy, and diabetic neuropathy." (PMID 38292764, 2023). "Therefore, further validation for the protein expression, kinase activity, function and molecular mechanism of HK2 in diabetic retinopathy was necessary in the future." (PMID 36557283, 2022).
influenza (4 papers, 2013 to 2024). An acute viral infection of the respiratory tract, occurring in isolated cases, in epidemics, or in pandemics; it is caused by serologically different strains of viruses (influenzaviruses) designated A, B, and C, has a 3-day incubation period, and usually lasts for 3 to 10 days. "The majority of the hits were novel; however, PANK4, NEK8, ITPKB, CALM2 and HK2 have been identified in other influenza screens." (PMID 23805279, 2013). "In addition, four of the six (HK2, NEK8, PANK4, PLK4) have also been identified important for influenza virus replication in other influenza-genome screens." (PMID 23805279, 2013).
retinal detachment (4 papers, 2017 to 2023). An eye emergency condition which may lead to blindness if left untreated. "HK2-deficient photoreceptors are more susceptible to acute nutritional deficiency in an experimental model of retinal detachment, and HK2 is important to maintain photoreceptor functions during aging." (PMID 37449059, 2023). "Furthermore, loss of HK2 leads to increased PR death following retinal detachment, demonstrating that the anti-apoptotic effects of HK2 is critical for cell survival during acute nutrient deprivation." (PMID 37626853, 2023). "Interestingly, we found that HK2-deficient photoreceptors are more susceptible to acute nutrient deprivation in the experimental retinal detachment model." (PMID 32499533, 2020). "In contrast, selective deletion of HK2 results in enhanced PR death after retinal detachment despite a compensatory increase in HK1 expression." (PMID 37626853, 2023). "In this report, we show that HK2 preferentially localizes to the mitochondria enriched fraction after outer retinal stress as produced by experimental retinal detachment." (PMID 32499533, 2020). "In this study, we show that HK2 translocates to mitochondria following retinal detachment and at the same time is significantly downregulated." (PMID 32499533, 2020). "Under acute outer retinal stress induced by experimental retinal detachment, HK2-to-HK1 isoform switching increases rod photoreceptor susceptibility to cell death." (PMID 32499533, 2020). "HK1 has been shown to have similar anti-apoptotic activity in non-retinal cells, but an increased expression of HK1 following the deletion of HK2 was unable to compensate for HK2-mediated neuroprotection, leading to increased PR death following retinal detachment." (PMID 37626853, 2023). "As total HK2 drops significantly after retinal detachment, the neuroprotective effect of HK2 mediated by mitochondrial regulation of apoptosis may be limited." (PMID 32499533, 2020). "Photoreceptors lacking HK2 are more susceptible to acute nutrient deprivation caused by retinal detachment." (PMID 32499533, 2020). "Here we show that following experimental retinal detachment, p-AKT is upregulated and HK2 translocates to mitochondria." (PMID 32499533, 2020). "One of the major non-enzymatic roles of HK2 is to inhibit binding of pro-apoptotic factors and prevent opening of the mPTP, which may explain why HK2 translocates to the mitochondrial fraction following retinal detachment." (PMID 32499533, 2020). "Unlike single knockout models, simultaneous deletion of HK2 and PKM2 does not alter PR survival when faced with acute nutrient stress following experimental retinal detachment." (PMID 37626853, 2023). "Selective deletion of HK2 and PKM2 did not impact PR survival during acute nutrient deprivation secondary to experimental retinal detachment." (PMID 37626853, 2023).
serous ovarian carcinoma (4 papers, 2018 to 2025). "Correspondingly, in primary cancer cells cultivated from high-grade serous ovarian carcinomas, the levels of HK1 and HK2 correlated at the mRNA and protein levels." (PMID 34895333, 2021).
triple-negative breast carcinoma (4 papers, 2017 to 2025). An invasive breast carcinoma which is negative for expression of estrogen receptor (ER), progesterone receptor (PR), and human epidermal growth factor receptor 2 (HER2). "An increase in hexokinase 2 (HK2) via EGFR activation contributes to aerobic glycolysis in triple-negative breast cancer cells." (PMID 33446631, 2021).
uveal melanoma (4 papers, 2018 to 2025). A melanoma derived from melanocytes of the uveal tract. "Hexokinase 2, a key enzyme in the glycolytic pathway, is also significantly overexpressed in both retinoblastoma and uveal melanoma, facilitating the shift to aerobic glycolysis, a hallmark of cancer cell metabolism." (PMID 40607060, 2025). "We observed a positive correlation between HK2 expression and the infiltration of Tfh for tumors of UVM (Uveal melanoma) and a negative correlation between BRCA, BRCA-LumA, HNSC, HNSC-HPV+." (PMID 36335239, 2022).
atherosclerosis (3 papers, 2020 to 2023). A disease characterized by the build-up of fatty material and calcium deposition in the arterial wall resulting in partial or complete occlusion of the arterial lumen. "In accordance with our findings, mRNA expression of glycolytic rate-limiting enzymes hexokinase 2 (HK2) and PFKFB3 is significantly elevated in monocytes isolated from patients with symptomatic atherosclerosis." (PMID 32350546, 2020). "Our findings on increased EC glycolysis were well correlated with a previous report that increased expression of HK2 is a proinflammatory phenotype only present in patients with symptomatic but not asymptomatic atherosclerosis." (PMID 36394956, 2023).
brain injury (3 papers, 2020 to 2025). Acute and chronic (see also brain INJURIES, CHRONIC) injuries to the brain, including the cerebral hemispheres, CEREBELLUM, and brain STEM. "For example, it has been reported that neurons are protected by restoring HK2-mediated glucose uptake during ischemic brain injury." (PMID 32602850, 2020). "Furthermore, studies demonstrated that injection of LND in animal models of ischemic brain injury 44 and OA 45 significantly reduced HK2 expression levels and exhibited anti-inflammatory effects." (PMID 39990654, 2025).
Cognitive impairment (3 papers, 2024 to 2025). Abnormal cognition is characterized by deficits in thinking, reasoning, or remembering. "Microglial HK2 levels were significantly elevated in the brains of those with AD, while HK2 deficiency resulted in increased ATP production of microglia, promoted microglia-mediated Aβ phagocytosis, and improved cognitive impairment in AD model mice." (PMID 40354372, 2025). "In SAE, OTUD1 deubiquitinates HK2, promoting its dissociation from mitochondria, which triggers microglia pyroptosis, leading to neuronal damage and cognitive impairment." (PMID 40500776, 2025).
colon adenocarcinoma (3 papers, 2021 to 2022). "Next, we searched the TCGA database and found that the NRF2 (NFE2L2) gene was positively correlated with the Warburg enzymes LDHA, PGK1, and HK2 in colon adenocarcinoma." (PMID 34094899, 2021). "However, HK2 was lower expressed in tumor tissues than in normal tissues of COAD (Colon adenocarcinoma), KICH, READ (Rectum adenocarcinoma), and THYM." (PMID 36335239, 2022). "In colon adenocarcinoma, tumors with higher T stage tended to have higher HK2 expression than tumor with lower stage (P = 0.07) and when categorizing tumors T1-3 versus T4, T4 tumors showed statistically significant HK2 overexpression, compared to T1-3 tumors (P = 0.015, data not shown)." (PMID 36320008, 2022).
heart failure (3 papers, 2021 to 2024). Inability of the heart to pump blood at an adequate rate to meet tissue metabolic requirements. "Studies have shown that increased HK2 activity after AMI is correlated with oxidative stress and increased left ventricular end-diastolic volume suggesting that HK2 may be involved in post-AMI heart failure." (PMID 38987688, 2024). "Heart failure also involves the development of vascular inflammation, and the sodium-glucose cotransporter 2 (SGLT2) inhibitor Canagliflozin (Cana) can reduce inflammation in endothelial cells via HK2 reductions, revealing that Cana has a novel anti-inflammatory mechanism via HK2." (PMID 37938421, 2023).
HIV-1 infection (3 papers, 2016 to 2023). The type species of lentivirus and the etiologic agent of acquired immunodeficiency syndrome (AIDS). "HIV-1 infection, also, at a transcriptional level, leads to the production of a fully glycosylated HK2 Env protein on the surface mononuclear cells of HIV-infected individuals." (PMID 34778024, 2021). "HIF-1α–activating genes, including HK2, PDK1, and LDHA (which function vitally in the glycolytic pathway), were also up-regulated by HIV-1 infection." (PMID 37798121, 2023). "Another group has shown that HIV-1 infection leads to increased transcription of HK2 proviruses, but did not verify the circulation of HK2 RNA in the plasma of HIV-1 infected patients." (PMID 27640347, 2016).
invasive breast carcinoma (3 papers, 2022 to 2025). A carcinoma that infiltrates the breast parenchyma. "Using multiple publicly available datasets, we found a significantly strong positive correlation between H2AX expression levels in patients with invasive breast cancer, and levels of glycolysis genes, particularly HK2." (PMID 35260660, 2022).
ischemic stroke (3 papers, 2025 to 2026). A stroke disorder caused by obstruction of blood flow to the brain, due to thrombotic (local blood clot formation) or embolic (due to a blood clot or other material traveling from another site) event. "In ischemic stroke, HK2 influences microglial metabolic reprogramming and inflammatory modulation: dexmedetomidine (DEX) pretreatment upregulates HK2, enhancing glycolytic flux and oxidative phosphorylation, which sustains microglial phagocytic capacity and promotes an anti-inflammatory phenotype." (PMID 41601478, 2026).